TTR (transthyretin)
Diseases named in the same sentence as TTR in open-access papers (continued):
Sharing a sentence is not in itself a finding about the gene and the disease.
amyloidosis (continued). "Serum amyloid A (SAA)-related (AA) amyloidosis is most frequently observed in autopsy cases, despite the fact that light chain-related amyloidosis and transthyretin (TTR)-related (ATTR) amyloidosis are arguably more common than it had been previously estimated." (PMID 36240260, 2022). "Amyloidosis, especially wild-type transthyretin (TTR) amyloidosis, is underdiagnosed in older people, for whom “red flags” may be misread and prognosis may be affected by diagnostic delays, despite available treatments." (PMID 36555671, 2022). "Tafamidis, a small molecule that inhibits the dissociation of transthyretin tetramers, was granted marketing authorization by China Food and Drug Administration for the treatment of inherited or wild type cardiac transthyretin amyloidosis in adult patients in 2020." (PMID 35833187, 2022). "Because the phenotypic expression, clinical course, and therapy for AL and TTR amyloidosis are quite different, it is desirable to develop a more comprehensive and specific diagnostic method that is capable of recognizing and distinguishing CA phenotypes early in the disease process." (PMID 36290299, 2022). "Hereditary transthyretin (hATTR) amyloidosis is an autosomal dominant genetic disorder characterized by the abnormal and excessive expression of TTR protein (produced mainly in the liver), which mis-folds and eventually aggregates into fibrils that deposit in numerous end organs." (PMID 36341129, 2022). "A few clinical studies have measured plasma TTR in patients with ATTRv or ATTRwt amyloidosis." (PMID 36009453, 2022). "Indeed, fibroblast and macrophages can endocyte and degrade TTR aggregates in lysosomes both in vitro and in vivo, thanks to their migratory potential and their proximity to amyloid deposits in ECM." (PMID 36009453, 2022). "In wild-type ATTR (ATTRwt) amyloidosis, the TTR gene sequence is preserved but TTR may become kinetically unstable due to a general aging-associated decrease in protein quality control mechanisms." (PMID 35386059, 2022). "Therefore, preclinical studies on mammalian models of TTR amyloidosis using a combination of santalol isomers are justified." (PMID 35784752, 2022). "Consistent with this, aging-associated oxidative modifications of amyloidogenic proteins such as TTR can destabilize the native protein and promote cytotoxic aggregation into toxic oligomers and amyloid fibrils, indicating a potential role for oxidative stress in TTR amyloid disease pathogenesis." (PMID 35191945, 2022). "Hereditary transthyretin (ATTRv) amyloidosis, also known as transthyretin-related familial amyloidotic polyneuropathy, is an autosomal dominant multisystem disease of adult onset characterized by systemic accumulation of mutant ATTR in organs and peripheral nerves." (PMID 36369333, 2022). "Hereditary amyloidogenic transthyretin (ATTR) amyloidosis with polyneuropathy, commonly known as transthyretin-type familial amyloid polyneuropathy (FAP), is a sparse condition mostly found in Japan, France, Portugal, Sweden, Spain, and descendants of these regions." (PMID 35784752, 2022). "Cardiac MRI is usually recommended to evaluate for cardiac involvement, but cannot distinguish AL from TTR forms of amyloidosis, and so an endomyocardial biopsy may be required." (PMID 36341129, 2022). "Indeed, kinetic stabilization of the native tetramer of transthyretin has resulted in the first small molecule therapy against a human amyloid disease." (PMID 36328246, 2022). "Recently, another study prepared NTLA-2001, an in vivo gene-editing therapeutic agent, made by lipid nanoparticles encapsulating messenger RNA of Cas9 protein and single guide RNA targeting misfolding transthyretin (TTR) responsible of transthyretin amyloidosis." (PMID 35958050, 2022). "TTR gene mutations could cause abnormal depolymerization, misfolding and aggregation of TTR, leading to amyloidosis formation." (PMID 36056432, 2022).
amyloidosis (continued). "Differently from TTR-amyloidosis, little is known about nerve involvement in acquired amyloidosis." (PMID 36388946, 2022). "The morpho-functional dissociation can be considered typical of TTR-amyloidosis neuropathy." (PMID 36388946, 2022). "Light chain (AL) and transthyretin (ATTR) amyloidosis are in the background in almost all cases." (PMID 35885070, 2022). "In addition, the increased aging of the population potentially fosters the cases of amyloidosis involving wt-TTR (SSA)." (PMID 35337074, 2022). "The development of successful formulations for delivery of siRNA inhibiting synthesis of transthyretin (TTR) in hepatocytes took at least two decades but became the first approved liposomal siRNA therapy for transthyretin-mediated amyloidosis, Patisiran (marketed as Onpattro)." (PMID 36411594, 2022). "In the first multicenter study of its kind, we have used hybrid PET/MR to investigate myocardial 18F-fluoride activity in patients with TTR amyloid, demonstrating increased uptake compared to age- and sex-matched controls and patients with both aortic stenosis and AL amyloid." (PMID 33000405, 2022). "This stage has been indicated as National Amyloidosis Centre (NAC) transthyretin amyloidosis stage." (PMID 35325395, 2022). "In addition, the present case broadens our understanding of the possible presence of a very rare TTR amyloidosis genotype." (PMID 35795194, 2022). "Such a multidisciplinary care model allows for the timely and effective diagnosis of amyloidosis, be it acquired amyloid light amyloidosis (AL), hereditary transthyretin amyloidosis (hATTR), or wild type amyloidosis (TTR-wt), especially in the current era of personalized genomic medicine." (PMID 36341129, 2022). "The phenotypical expression of an European inherited TTR amyloidosis in Brazil." (PMID 35262576, 2022). "However, the increase in Troponin I was comparable to the TRACS (Transthyretin Amyloidosis Cardiac Study) study where a group of untreated TTR-CM patients had a similar elevation in Troponin I." (PMID 34703707, 2021). "TTR amyloidosis (ATTR) is a progressive fatal disease, which may be inherited in an autosomal dominant manner through inheritance of one of more than 100 recognised pathogenic mutations in the TTR protein." (PMID 34539755, 2021). "To validate the efficacy of thyromimetic molecules for TTR amyloidosis, we first tested whether GC-1, IS25, and TG68, are able to repress the aggregation propensity of TTR." (PMID 33800546, 2021). "siRNAs formulated as a lipid complex or covalently linked to specific ligands enabled FDA approval of ONPATTRO® (patisiran) for treatment of polyneuropathy in patients with hereditary transthyretin-mediated amyloidosis and GIVLAARITM (givosiran) used for treatment of acute hepatic porphyria (AHP)." (PMID 34063475, 2021). "The literature describes many types of systemic amyloidosis, four of which are seen most frequently: AL (immunoglobulin light chain amyloidosis), AA (also known as secondary amyloidosis), ATTR (transthyretin amyloidosis), and Aβ2M (Beta-2 Microglobulin amyloidosis)." (PMID 34641582, 2021). "However, among the amyloidosis subtypes, transthyretin amyloidosis (ATTR) wild type generally present the worst reservoir and contractile function." (PMID 35096989, 2021). "Given the involvement of TTR in the vitamin A retinal metabolism and visual cycle, it is conceivable to hypothesize that in TTR-related amyloidosis, retinal function abnormalities can be present at an early stage of the disease." (PMID 34207092, 2021). "Within the disease context, the detection of a mutation allows one to classify TTR amyloidosis as hereditary rather than wild-type and should prompt consideration for genetic screening of siblings." (PMID 34380564, 2021).
amyloidosis (continued). "Two individuals (2 of 157; 1.3%) with a P/LP TTR variant (T60A [same patient as above] and V122I) had a diagnosis of noncardiac-specific (general) amyloidosis compared to 136 controls without a P/LP TTR variant (136 of 134,596; 0.1%)." (PMID 34746851, 2021). "In the NEURO-TTR trial, three cases (3%) of severe thrombocytopenia, including one in association with a fatal intracranial hemorrhage, were observed during therapy with inotersen, an ASO designed to inhibit hepatic production of transthyretin in patients with hereditary transthyretin amyloidosis." (PMID 33899154, 2021). "Despite the increasing interest in TTR proteolysis as a leading mechanism-driving TTR amyloidosis, some questions remain to be answered, namely whether TTR fragmentation occurs, prior to or after TTR aggregation/deposition and where it occurs." (PMID 34502397, 2021). "There are two major forms of amyloidosis: amyloid light-chain and transthyretin amyloidosis." (PMID 34917152, 2021). "TTR amyloidosis can be due to wild-type (ATTRwt, no mutation, previously called “senile cardiac amyloidosis”) or a hereditary genetic variant of TTR (ATTRm), of which there are currently more than 100 described." (PMID 33817700, 2021). "In addition, proteolysis-induced fragmentation of TTR, a recently proposed mechanism facilitating TTR amyloidosis, has been discussed in light of its structural consequences and relevance to acknowledge the amyloidogenicity of TTR." (PMID 33922648, 2021). "Yet, it may indicate heterogeneous amyloidosis mechanisms of TTR that are likely to depend on factors such as genetic variations and conditions of aggregation." (PMID 33922648, 2021). "In addition, it should be stressed that this study needs to be followed by additional in vitro and in vivo experiments considering various aspects of TTR amyloidosis and the related pathology." (PMID 33800546, 2021). "Several types are known, of which AL (light chain) amyloidosis and TTR (transthyretin) amyloidosis may affect the heart." (PMID 34524619, 2021). "In contrast, moderately unstable, but still amyloidogenic TTR variants (e.g., L559 TTR), may escape the ER QCS of the liver and be secreted at levels suitable to develop amyloidosis." (PMID 34884963, 2021). "Non-genetic forms of amyloidosis with cardiac involvement are, for example, the ATTRwt amyloidosis (criterion: exclusion of a TTR gene mutation) and ANF-associated amyloidoses (AANF), which manifest primarily as atrial cardiomyopathy." (PMID 33459839, 2021). "In more recent years, TTR gene silencing therapy with an antisense oligonucleotide (ASO) (inotersen) or a small interfering RNA (siRNA) (patisiran) appeared as a more promising therapeutic strategy for hATTR amyloidosis." (PMID 33921571, 2021). "First, the mechanistic details of TTR amyloidosis remain to be further elucidated." (PMID 33922648, 2021). "Hereditary transthyretin (hATTR) amyloidosis is a rare, systemic, progressive, and life-threatening disease in which transthyretin (TTR) proteins misfold and aggregate as insoluble amyloid deposits, disrupting nervous, cardiac, and other organ tissues throughout the body." (PMID 33411323, 2021). "Genetic analysis revealed absence of any mutant variant/s of transthyretin gene, confirming wild-type transthyretin amyloidosis." (PMID 33907095, 2021). "However, the real prevalence of transthyretin amyloidosis should be higher, considering that about 25% of patients aged more than 80 years show myocardial wild-type transthyretin fibrils in autopsy studies." (PMID 34299270, 2021). "TTR amyloidosis may be facilitated by local mechanisms operating under different conditions, including pH and temperature." (PMID 34884963, 2021). "As this observation was made at pH ~3, it is probable that TTR amyloidosis may be facilitated by a distinctive mechanism under different conditions." (PMID 33922648, 2021).
amyloidosis (continued). "The recent FDA approval of Patisiran represents a first-of-its-kind RNA interference (RNAi) therapeutic for the treatment of the polyneuropathy of hereditary transthyretin-mediated (hATTR) amyloidosis in adults and the first ever FDA approval of a siRNA treatment." (PMID 33481821, 2021). "In addition to TTR, there are other rarer forms of hereditary amyloidosis, including lysozyme and gelsolin amyloidosis." (PMID 34106429, 2021). "SEC of aged TTR samples indicated that monomeric TTR could be converted into still monomeric, yet structurally different species during TTR amyloidosis." (PMID 33922648, 2021). "Modified from: Recent advances in transthyretin amyloidosis therapy, Mitsuharu Ueda and Yukio Ando." (PMID 34206500, 2021). "However, in hATTR amyloidosis, both mutant and wild-type TTR deposit as amyloid in peripheral nerves and in many other organs, including heart, kidney, and gastrointestinal tract." (PMID 33921571, 2021). "So far, no data exist on the TTR mutation frequency in German amyloidosis patients with cardiac involvement." (PMID 33459839, 2021). "In addition, the proteolysis-induced fragmentation of TTR was recently proposed as an efficient mechanism facilitating TTR amyloidosis even in a physiological pH." (PMID 33800546, 2021). "In wild-type TTR amyloidosis, in general older age precludes heart transplantation." (PMID 34524619, 2021). "The efficacy of these molecules was tested in a mouse model and in the observational studies of human patients, indicating that these molecules may constitute a novel repertoire for TTR amyloidosis therapeutics." (PMID 33800546, 2021). "This disease mainly consists of hereditary ATTR (ATTRv; v stands for variant) amyloidosis, alternatively known as familial amyloid polyneuropathy, and wild-type ATTR (ATTRwt) amyloidosis, also known as senile cardiac or systemic amyloidosis, based on the presence or absence of a mutation in TTR." (PMID 34361762, 2021). "Hereditary transthyretin (hATTR) amyloidosis is a rare, systemic, progressive, and life-threatening disease in which transthyretin proteins misfold and aggregate as insoluble amyloid deposits, disrupting nervous, cardiac, gastrointestinal, and other organ tissues." (PMID 33411323, 2021). "Individuals with P/LP TTR variants identified by genomic screening have increased odds of heart disease after age 60 years, although amyloidosis is likely underdiagnosed without knowledge of the genetic variant." (PMID 34746851, 2021). "Onpattro® is currently approved to treat transthyretin-mediated (ATTR) amyloidosis." (PMID 33271886, 2020). "Light-chain (AL) and transthyretin (ATTR) amyloidosis have different disease trajectories." (PMID 31134330, 2020). "TTR amyloidosis and the accumulation of Aβ peptide in the eye could be considered as antigens; however, the interior of the eye is an immunoprivileged site." (PMID 32566091, 2020). "Furthermore, IgM from healthy donors can hydrolyze the transthyretin protein, which forms aggregates and leads to amyloidosis development." (PMID 32751323, 2020). "The nature of factors initiating onset of amyloidosis is not currently known for any of these diseases, However, the common features suggests that a model developed for TTR amyloidosis may be applied in analysis of the other heritable amyloidosis diseases." (PMID 33203794, 2020). "The Phase 3 ENDEAVOUR study was designed to investigate the effect of revusiran, a first-generation GalNAc–siRNA conjugate targeting TTR, in patients with hATTR amyloidosis with cardiomyopathy, a debilitating condition with an average life expectancy of a median 3.4 years from diagnosis." (PMID 32062791, 2020). "Additionally, a greater reduction in deceleration time of early filling, and a lower indexed LV mass, have been reported in AL in comparison to TTR amyloidosis, assisting the differentiation of the two pathologies." (PMID 33195479, 2020).
amyloidosis (continued). "Mutant-specific differences in oligomer/fibril binding to cellular membranes could explain differing phenotypic patterns of TTR amyloidosis." (PMID 33203794, 2020). "TTR is implicated in several acquired and hereditary amyloid pathologies (ATTR, TTR amyloidosis)." (PMID 33287192, 2020). "Transthyretin (TTR) variant amyloidosis (ATTRv) is an autosomal dominant disease characterized by the formation and storage of amyloid aggregates in many organs, mostly causing an axonal sensory-motor neuropathy, cardiomyopathy, gastrointestinal dysfunction, and dysautonomia." (PMID 32655365, 2020). "TTR amyloidosis shares common characteristics with other amyloid diseases, such as Alzheimer’s, spongiform encephalopathies, or Parkinson’s, where soluble peptides or proteins undergo conformational changes and aggregate into insoluble and highly stable amyloid fibrils." (PMID 33287192, 2020). "Risk of transthyretin-mediated amyloidosis is enhanced by age and mutation of the transthyretin (TTR) gene, but amyloidosis is not directly initiated by mutated TTR proteins." (PMID 33203794, 2020). "In 2018, the siRNA–lipid nanoparticles delivery system was approved as part of the product Patisiran (Onpattro, Alnylam Pharmaceuticals, Cambridge, MA, USA) for patients with hereditary transthyretin-mediated amyloidosis to inhibit hepatocyte expression of transthyretin." (PMID 33396817, 2020). "Indeed, cardiac amyloid deposits containing TTR can be detected in 12–25% of subjects older than 80 years at autopsy." (PMID 32754033, 2020). "The various forms of amyloidosis require different treatment approaches, including high-dose melphalan with stem cell transplantation in AL amyloidosis, and liver transplantation or use of transthyretin (TTR)-tetramer stabilizer in hereditary TTR amyloidosis." (PMID 32609750, 2020). "Patisiran, an RNA interference therapeutic, has demonstrated robust reduction of wild-type and mutant transthyretin protein and was able to improve polyneuropathy and quality of life following 18 months of treatment in patients with hereditary transthyretin-mediated (hATTR) amyloidosis." (PMID 32641071, 2020). "The exact mechanism is largely unknown but is hypothesized to be due to binding of calcium in TTR amyloidosis fibrils to the phosphate domains in injected tracers." (PMID 33195479, 2020). "Data from the Phase 3 APOLLO study of patisiran support the therapeutic hypothesis of TTR reduction as a potential approach for treatment of cardiomyopathy in hATTR amyloidosis." (PMID 32062791, 2020). "Transthyretin (TTR) amyloidoses are a group of systemic degenerative diseases involving multiple organ systems and are caused by TTR aggregation, such as familial amyloid polyneuropathy (FAP), familial amyloid cardiomyopathy (FAC), senile systemic amyloidosis and leptomeningeal amyloidosis." (PMID 32998442, 2020). "The two most common subtypes are light-chain and transthyretin amyloidosis." (PMID 33195479, 2020). "Therefore, brief summaries of relevant information on the TTR protein properties and TTR amyloid diseases are given here with only limited further references." (PMID 33203794, 2020). "We therefore hypothesize that the age-related imbalance in proteolysis initiates TTR amyloid diseases." (PMID 33203794, 2020). "However, in August 2018, the FDA approved OnpattroTM (patisiran), the first siRNA-based drug for the treatment of hereditary TTR-mediated amyloidosis (hATTR)." (PMID 32760425, 2020). "Furthermore, autopsy samples revealed a prevalence of transthyretin amyloidosis of 10%–25% in the elderly (age >80 years), proving ATTR is clearly underdiagnosed." (PMID 31083399, 2019). "Similarly, CLR01 was found to reduce transthyretin (TTR) toxic aggregates involved in transthyretin amyloidosis." (PMID 31075983, 2019).